KLF9 (KLF transcription factor 9)
Diseases named in the same sentence as KLF9 in open-access papers (continued):
Sharing a sentence is not in itself a finding about the gene and the disease.
cancer (continued). "KLF9-bound genomic regions, along with those of SP1, CTCF, NRF1, GABPA, and YY1, were found to exhibit resistance to de novomethylation in cancers, likely due to their role in maintaining open chromatin or recruiting epigenetic modifiers." (PMID 40860800, 2025). "Mechanistically, KLF9 inhibits the transcription of matrix metalloproteinase 28 (MMP28), a protein that facilitates cancer cell invasion." (PMID 40860800, 2025). "The increased interest that KLF9 and KLF13 have received in the oncology world portends an even more exciting future for these proteins in cancer prevention and treatment." (PMID 38067370, 2023). "The present review, in contrast, concentrates on the paralogous KLF9 and KLF13, their known roles in the suppression or promotion of cancer development, and the current gaps in knowledge regarding their respective biology, signaling, and oncogenic mechanisms." (PMID 38067370, 2023). "Elucidation of KLF9 and KLF13 in cancer biology is likely to provide new inroads to the understanding of oncogenesis and its prevention and treatments." (PMID 38067370, 2023). "Another pathway that integrally utilizes KLF9 and KLF13, and which has potential implications in oncogenesis and cancer therapy, is the circadian clock." (PMID 38067370, 2023). "Lastly, with respect to the future drugging of KLF9 and KLF13 for possible applications in cancer therapies, one goal would be to identify small molecule inducers of these mRNAs/proteins in pre-neoplastic and malignant cells." (PMID 38067370, 2023). "Here, we describe the salient features of KLF9 and KLF13, the current state-of-the-art research regarding both protein’s actions in cancer development and response to therapies, and where the field requires further exploration." (PMID 38067370, 2023). "An examination of a current DNA methylation database (MethHC 2.0) indicates that KLF9 and KLF13 gene promoter regions are over- or under-methylated in small subsets of human cancers." (PMID 38067370, 2023). "To investigate the impact of the GC signaling and KLF9 in BCa etiology, we treated the KLF9 knockdown and overexpression lines with CORT prior to functional analysis using assays of cancer hallmarks including survival, proliferation, apoptosis, and migration." (PMID 36823570, 2023). "KLF9 suppresses hepatic oxidative stress and inflammation, thus identifying potential mechanisms for KLF9 suppression of HCC and perhaps cancers of other tissues." (PMID 35406507, 2022). "Consequently, KLF9 may have a distinct role in various cancer types." (PMID 36186479, 2022). "While the emCpGs harbour enriched binding sites for their specific emTFs, the non-correlated CpGs shared a binding signatures for SP1, CTCF, NRF1, GABPA, KLF9, and YY1 providing a protective effect against de novo methylation across cancer types." (PMID 35440061, 2022). "Although studies have shown that KLF9 can inhibit the proliferation, migration, and invasion of cancer cells, its specific molecular mechanism has not been fully elucidated." (PMID 40860800, 2025). "KLF9 has been shown to modulate immune responses within the TME, interact with CAFs, and affect the formation of new blood vessels, making it a pivotal player in the dynamics of cancer progression and metastasis." (PMID 40860800, 2025). "While KLF9 consistently inhibits oncogenic processes, such as EMT, cancer stemness, and immune evasion, its regulatory networks exhibit tissue-specific complexity, governed by microRNAs (miRNAs), long non-coding RNAs (lncRNAs), and post-translational modifications." (PMID 40860800, 2025). "On the other hand, our analysis showed that the GALNT7, KLF9, and DAB2 genes may be particularly critical as ceRNAs in three cancer tissues." (PMID 38627780, 2024). "Finally, the stimulation of Kruppel-like factor 9 (Klf9) by ROS on nuclear factor erythroid 2-related factor 2 (Nrf2) leads to the activation of ERK1/2 and an increase in ROS generation in cancer cells." (PMID 38338912, 2024).
cancer (continued). "The results of the study revealed that the miRNA:ceRNA interaction consisting of 63 genes and 165 miRNAs is common to all three cancer tissues and that the GALNT7, KLF9 and DAB2 genes may be involved in critical ceRNA interactions in all three cancer tissues." (PMID 38627780, 2024). "More specifically, in this core interaction network, ceRNAs such as GALNT7, KLF9, and DAB2 and miRNAs like miR-106a/b-5p, miR-20a-5p, and miR-519d-3p may have potential as common targets in the three critical cancers." (PMID 38627780, 2024). "Silencing of miR-218-5p inhibited activation of the JAK2/STAT3 pathway by targeting KLF9, while KLF4, which belongs to the same family, could inhibit the JAK2/STAT3 pathway, which in turn affects cancer cell development." (PMID 37465460, 2023). "It seems reasonable that such complexes, along with changes in KLF phosphorylation and acetylation status (more for KLF13 than KLF9), will underpin the convergence of signaling pathways as well as growth and nutrient signals at the level of KLF target genes in pre-cancerous and cancer cells." (PMID 38067370, 2023). "This highlights the limitations of targeting KLF9, as a single target may not be sufficient to completely block cancer progression." (PMID 40860800, 2025). "However, a mechanistic basis for how KLF9 decreases cancer initiation/development has not been elucidated." (PMID 35406507, 2022). "Additionally, although the individual expression status of TPD52, KLF9, miR-223, and PKCε has been previously studied in various tumors, no study has investigated the co-expressions of TPD52, KLF9, miR-223, and PKCε in any cancer type." (PMID 35047407, 2021). "The earliest study in this area described the effect of KLF13, but not KLF9, on increasing the apoptosis of PANC1 cancer cells in vitro." (PMID 38067370, 2023). "In contrast, KLF9 does not oscillate in entrained MDA-MB-231 cells and circadian expression of BMAL1 and PER1 was slightly irregular in the cancer cell line as well." (PMID 36823570, 2023). "Unlike most cancer types, NPC tumors are reported to have significantly higher levels of KLF9 mRNA than the corresponding normal tissue." (PMID 38067370, 2023). "In the cases of KLF9 and KLF13, this discordance has not been thoroughly examined for numerous cell or tissue types (including cancers), but this possibility should be considered when assigning function based solely on assays of mRNA abundance." (PMID 38067370, 2023). "To date, this information is absent for KLF9 and KLF13 in most human cancers." (PMID 38067370, 2023).
infection (4 papers, 2018 to 2025). The state of being infected such as from the introduction of a foreign agent such as serum, vaccine, antigenic substance or organism. "Additional studies are also required to determine whether loss of Klf9 alters the function of immune cells or the inflammatory response to injury or infection." (PMID 32651405, 2020). "Consistently, the grip strength of Klf9 transgenic mice improved after AAV2/8‐dnMstn infection." (PMID 40717541, 2025). "Lv-Klf9 and Lv-KLF9 infection significantly increased KLF9 expression in macrophages." (PMID 38331933, 2024).
degenerative diseases (2 papers, 2025). "Moreover, Klf9, Foxo1, and Clock, which play significant roles in neurodegenerative diseases and age-related cognitive decline, regulate downstream genes associated with neurogenesis, synaptic plasticity, and membrane potential." (PMID 41450877, 2025). "In the current study, we conducted bioinformatics analysis by using the GEO database and found that the expression of KLF9 in OA samples was significantly downregulated; this finding was consistent with previous studies on KLF9 in other inflammatory diseases and degenerative diseases." (PMID 40533763, 2025).
heart disease (2 papers, 2022 to 2025). "Recent studies have revealed the role of KLF9 in some heart diseases." (PMID 40198141, 2025). "The transcription factors such as KLF9 (Kruppel-like factor 9) and Nrf2 (nuclear factor erythroid-2 related factor 2), which control the development of oxidative stress and the expression of antioxidant genes, have been reported to be activated in heart disease, respectively." (PMID 35203602, 2022).
neurologic diseases (2 papers, 2022 to 2023). "Although the important roles of KLF9 in neurologic diseases have been revealed, its detailed function and the underlying mechanism in SCI remain unclear." (PMID 37940560, 2023). "KLF9 is a member of the KLF family and plays an important role in neurologic disorders." (PMID 37940560, 2023).
cardiovascular disease (1 paper, 2022). "These contradictory results indicate the associated effects of KLF9 on redox balance in cardiovascular disease, especially DCM." (PMID 36359788, 2022).
prostate (1 paper, 2022). "However, another study reported that miR141 significantly reduced cell apoptosis, thus appearing to be a novel oncogene miRNA, which promotes prostate tumorigenesis via suppressing a key transcription factor kruppel-like factor-9 (KLF9)." (PMID 36158660, 2022).
KLF9 also shares sentences with these, for which no sentence is quoted: colon cancer (2 papers); colorectal tumors (2); Infertility (2); Insulin resistance (2); oral squamous cell carcinoma (2); acute kidney injury (1); acute lymphoblastic leukaemia (1); acute myeloid leukemia (1); anaemia (1); asthma (1); autoimmune thyroid disease (1); B cell CLL (1); blood cancers (1); brain tumors (1); cardiac hypertrophy (1); clear cell renal cell carcinoma (1); COVID-19 (1); gynecological tumors (1); Hyperkeratosis (1); hyperlipidemia (1); inflammation (1); iron deficiency (1); ischemia (1); joint disorders (1); kidney cancer (1); kidney injury (1); lung adenocarcinoma (1); Lung squamous cell carcinoma (1); metabolic disease (1); metastatic diseases (1).
A further 12 diseases each share a sentence with KLF9 in 1 paper.